LINC00501 (long independently transcribed non-coding RNA 501)
Gene: Long non-coding RNA gene on chromosome 3 (177,294,378 to 177,338,095, forward strand). Ensembl gene ENSG00000203645.
Diseases named in the same sentence as LINC00501 in open-access papers:
LINC00501 is named in the same sentence as 4 diseases in open-access papers, as found by Europe PMC text mining. Sharing a sentence is not in itself a finding about the gene and the disease. The quoted sentences say what the papers report.
lung carcinoma (2 papers, 2022 to 2025). "LINC00501 was overexpressed in lung cancer (LC) and related to poor OS of LC patients." (PMID 41431049, 2025). "LINC00501 involved in the progression and development of lung cancer." (PMID 36072979, 2022).
non-small cell lung carcinoma (1 paper, 2022). A group of at least three distinct histological types of lung cancer, including non-small cell squamous cell carcinoma, adenocarcinoma, and large cell carcinoma. "Research showed that LINC00501 is highly expressed in non-small-cell lung cancers and patients with high LINC00501 expression had worse prognosis." (PMID 36072979, 2022).
tumour (1 paper, 2023). "Since P300 plays a vital part in the abnormally increased levels of LINC00501 in GC, we next testify whether the pharmacological intervention of P300 activity with C646 could impact the expression of LINC00501 and GC tumour growth." (PMID 37867401, 2023). "Importantly, inhibition of LINC00501 by lentivirus or P300 inhibitor C646 significantly suppressed tumour growth of GC, which indicates that targeting P300/LINC00501 axis may be an optional target for GC." (PMID 37867401, 2023). "Our study revealed that LINC00501 is highly expressed in GC and promotes GC metastasis by enhancing the EMT process and tumour environment remodel." (PMID 37867401, 2023). "In our study, we demonstrated that disruption of the P300/LINC00501 axis by C646 inhibits the tumour growth of GC without significant sign of side effect, indicating that the P300/LINC00501 axis as a therapeutic target in GC." (PMID 37867401, 2023).
LINC00501 also shares sentences with these, for which no sentence is quoted: gastric cancer (1 paper).